MUC1 (mucin 1, cell surface associated)
Diseases named in the same sentence as MUC1 in open-access papers (continued):
Sharing a sentence is not in itself a finding about the gene and the disease.
tumor (continued). "Moreover, the aberrant tumor-associated MUC1 can contribute to the change in MUC1 downstream signals through its cytoplasmic domain, which further regulates different aspects of tumor functions (cell growth, proliferation, developmental processes, metastasis, apoptosis, etc.)." (PMID 37489369, 2023). "Thus, the association of low CA27.29 values and poor prognosis of node-positive patients with advanced tumor stage (pT3/4) might be due to the loss of the MUC1-regulated immune response." (PMID 35406491, 2022). "In addition, overexpression of MUC1 or MUC13 rescued GSDME-deficiency-retarded tumour growth." (PMID 35292781, 2022). "The results of this study explain MUC1-EMA epitope may be associated with a poor prognosis that might be a strong relationship with tumor angiogenesis required not only for continued tumor growth but also for invasion and metastasis and may be modified by androgens and estrogens receptors." (PMID 35646176, 2022). "Notably, mAb TAB004 can identify the changed glycosylated epitope in the MUC1 TP sequence, with the STAPPVHNV sequence being the binding epitope, suggesting the high specificity of TAB004 for tumor-associated MUC1 and its inability to recognize healthy epithelium." (PMID 35883508, 2022). "Furthermore, glycosylated MUC1 is associated with higher tumor grades and poor prognosis." (PMID 35970845, 2022). "In addition, MUC1 absence is associated with altered tumour microenvironment (TME)." (PMID 35910854, 2022). "In addition to a gene signature associated with stemness and EMT we were able to identify tumor markers that are used in clinical trials, such as mucin 1 (MUC1; used to monitor metastasis in patients) and members of the carcinoembryonic antigen (CEA) related cell adhesion molecules (CEACAM) family." (PMID 33668737, 2021). "Furthermore, tumor associated MUC1 has drastically shorter O-glycans in the tandem repeat region of MUC1 made of 20-amino acid residues (APDTRPAPGSTAPPAHGVTS), which leads to the exposure of the protein core, rendering it a highly attractive antigen for anti-cancer immune-therapy." (PMID 32351942, 2020). "In a trial, HER2 and MUC1 specific CARs with CD3z and co-stimulatory molecule respectively within one T cell have been designed, which can eliminate tumor cells efficiently and offset tumor antigen escape variants when encountering target cells co-expressing MUC1 and HER2." (PMID 29568411, 2018). "Mucin1 (MUC1) encodes a glycoprotein that has been demonstrated to have important roles in cell‐cell interactions, cell‐matrix interactions, cell signaling, modulating tumor progression and metastasis, and providing physical protection to cells against pathogens." (PMID 30460337, 2018). "We showed that tumor-derived MVs carrying the MUC1 tumor glycoantigen employed as immunogen, restored phagosomal pH close to neutrality, allowing cross-presentation of the tumor associated MUC1 glycoantigen and the activation of MUC1 specific CD8+ T cell response." (PMID 30455687, 2018). "Also the rMUC1 carrying tumor-associated glycans was employed as soluble MUC1 form." (PMID 28993771, 2017). "Moreover, overexpression of MUC1 on tumor cells is associated with tumor metastasis." (PMID 26344745, 2014). "In this regard, exogenous or tumor-derived galectin-3 was shown to increase melanoma and colon cancer cells homotypic and heterotypic adhesions by interaction with oncofetal Thomsen–Friedenreich carbohydrate on the cancer-associated transmembrane mucin protein (MUC1)." (PMID 24982845, 2014). "Therefore, mimicry of the Gal-epitope by MUC1 might skew Th2 type responses to MUC1 vaccines, which is contradictory to the present paradigm that stresses Th1 responses as being beneficial to MUC1 and other tumor-associated antigens." (PMID 25071769, 2014). "Thus a close association of HSP70 and MUC1 exists in tumor cells." (PMID 22912777, 2012).
tumor (continued). "Importantly, the role of MUC1 in metastasis is associated with its intracellular domain, which enters the nucleus and initiates the transcription of a program of genes that modulate tumor metastasis." (PMID 22586492, 2012). "Similarly for epithelial-type CTCs, tumor associated MUC1 may play the role of beta-2 integrins on leukocytes by binding ICAM-1 to enable firm adhesion and initiate subsequent events in the metastatic cascade." (PMID 22866263, 2012). "Therefore, while MUC1 over-expression is associated with subpopulations of cells with elevated intrinsic Δψm, it is not directly linked to the generation or maintenance of stable alterations in intrinsic Δψm, or to intrinsic Δψm associated tumor phenotypes." (PMID 21966455, 2011). "Our data demonstrate that while elevated constitutive MUC1 is associated with subpopulations of cells with elevated intrinsic Δψm, MUC1 is not directly linked to the generation or maintenance of stable alterations in intrinsic Δψm, or to intrinsic Δψm associated tumor phenotypes." (PMID 21966455, 2011). "Thus, tumor-associated MUC1 is a promising molecular target for a novel therapy for EOC patients." (PMID 21931707, 2011). "The findings of Graves and colleagues that abs purified against tumor-associated MUC1 display a wider range of polyclonality than abs purified against a MUC1 peptide, and are more discriminatory between normal and tumor-associated MUC1 also support this notion." (PMID 24212946, 2011). "MUC1 overexpression and the aberrant cell surface glycosylation associated to it play a role in cancer progression by altering adhesion and anti-adhesion of tumor cells, therefore favoring invasion of lymph and blood vessels by tumor cells, and extravasation of tumor cells at distant sites." (PMID 24212946, 2011). "CA15-3 (Cancer Antigen 15 − 3) is the soluble form of MUC1, it is detectable in serum and is the most widely used tumor marker for breast cancer." (PMID 41533164, 2026). "Overall, our results showed that MUC1H cancer cells induced an increased angiogenesis compared to MUC1L cancer cells, although MUC1-expressing tumor cells were more sensitive to antineoplastic effects of sunitinib than MUC1L cells." (PMID 41533164, 2026). "Previous studies have shown that DNA methylation regulates MUC1, identifying it as an epigenetically controlled gene, and that promoter methylation of mucins, including MUC1, generally decreases across tumours." (PMID 41562704, 2026). "MUC1 expressing ccRCC is a high angiogenic tumor that presents characteristics of increased aggressiveness, and a specific metabolic profile." (PMID 41533164, 2026). "Preclinical studies on adjuvanted MUC1 subunit vaccines have shown their antitumor activities by inducing Th1 and NK cell response to suppress tumor cells in mice models." (PMID 40699805, 2025). "Given its elevated expression in HNSCC, targeting MUC1 with CAR-T cells offers a promising approach to specifically eliminate tumor cells while sparing normal tissues." (PMID 40312353, 2025). "These cells are associated with a reduction in the adaptative immune response to tumor MUC1 by lowering the production of specific antibodies and reducing the activation and proliferation of tumor‐specific T cells while stimulating Treg development." (PMID 40033767, 2025). "Instead, in tumor tissues, MUC1 is aberrantly expressed and glycosylated and its localization is altered." (PMID 40001578, 2025). "Because MUC1 is found on the cell surface and often hypoglycosylated in cancer, an antibody response has the potential to lead to reduced tumor growth." (PMID 40284463, 2025). "mRNA-based vaccines targeting MUC1 aim to induce tumor-specific immune responses, while siRNA-mediated silencing of CTLA-4 offers a more targeted approach to immune modulation." (PMID 40943370, 2025). "This strategy effectively targets MUC1-overexpressing tumor cells, leading to efficient anti-tumor responses while minimizing off-target effects." (PMID 40069884, 2025).
tumor (continued). "The findings indicate that MUC1 promotes tumor growth by affecting multiple signaling pathways such as PI3K/AKT, MEK/ERK, and WNT/β-catenin, among others." (PMID 40699746, 2025). "Mucin 1 (MUC1) is abnormally expressed in cancers, allowing it to be used as a tumor marker for the early diagnosis of cancer." (PMID 41149305, 2025). "For example, elevated levels of antigens like Tn, STn, and Lewis antigens on mucins like MUC1, MUC4, and MUC16 have been linked to enhanced tumor metastasis." (PMID 40868286, 2025). "This phenomenon is particularly evident with MUC1, where altered glycosylation can enhance its immunogenicity, leading to modulation of the immune landscape within the tumor." (PMID 40655139, 2025). "Mucin 1 (MUC1), a membrane-tethered glycoprotein expressed in glandular epithelial tumors of gastrointestinal origin, has been targeted for tumor immunotherapy." (PMID 40801739, 2025). "Tumor stroma interface: aberrant MUC1/MUC16 sialylation ligates inhibitory Siglec-7/9 on T and NK cells, promoting functional exhaustion; a CAF-rich stroma further enforces exclusion." (PMID 41228299, 2025). "Various tumor antigens—including VEGFR2, EGFR, HER2, MAGE, MUC1, FGFR, Flt4, and tumor-associated carbohydrate antigens—have been used in preclinical vaccine candidates." (PMID 40427029, 2025). "Another promising antigen is Mucin 1 (MUC1), a heavily glycosylated glycoprotein found on the surface of many tumor cells." (PMID 40013133, 2025). "Patients with MUC1 overexpression had a higher rate of deeper tumor depth (T staging), lymph node metastasis (N staging), and distant metastasis (M staging)." (PMID 41154387, 2025). "Higher MUC1 expression associated with increased infiltration of macrophages, mature and immature monocytic cells, and granulocytes in MMR-proficient tumours." (PMID 39966658, 2025). "Lastly, multi-immunofluorescence staining revealed interactions between SIGLEC9+ T-cells and MUC1 in the tumor microenvironment." (PMID 41418390, 2025). "What makes MUC1 a particularly interesting target for IgA mAbs is its tumor-specific expression of the sialyated core 1 glycan (MUC1-ST), which interacts with Siglec-9 on myeloid cells." (PMID 40358156, 2025). "At the same time, MUC1 is involved in regulating the tumor microenvironment by modulating the expression of CD274/PD-L1." (PMID 40655139, 2025). "After vaccination, MUC1.Tg mice were inoculated with LLC cells as a tumor challenge model to assess the induction of an immunogenic and anti-tumor response." (PMID 40284463, 2025). "Macrophages expressing Siglec-9 interact with sialylated MUC1 on tumor cells, promoting a protumorigenic phenotype through the release of factors such as interleukin-6 and macrophage colony-stimulating factors." (PMID 40443562, 2025). "In line with TAA expression on PDAC cell lines, EpCAM, TROP2 and MUC1 were the most abundant expressed TAA on patient tumor cells." (PMID 40358156, 2025). "In this regard, treatment with anti-TGF-β neutralizing antibody leads to a significant reduction in the tumor growth of xenograft mice models characterized by high-MUC1 neoplasia." (PMID 40001578, 2025). "Taken together, these results demonstrate that MUC1 promotes the symmetric division of tumor spheroidal cells." (PMID 40349179, 2025). "The resulting MUC1‐decorated DEX elicited the production of MUC1‐specific IgG antibodies exhibiting high‐affinity binding toward MUC1‐overexpressing tumor cells, thereby promoting potent antigen‐specific immune responses in vivo." (PMID 41256221, 2025). "This phenomenon is characterized by the aberrant localization of secretions and blebs on the basal surface of tumor cells, along with MUC1 (Mucin1) (EMA) immunostain expression, which distinguishes IMPC from other breast carcinoma subtypes." (PMID 41583217, 2025).
tumor (continued). "Emerging solutions, such as dual-target CAR-T cells that simultaneously recognize two tumor-associated antigens (e.g., HER2/MUC1 or B7-H3/CD276), aim to counter antigen escape, enhance specificity, and reduce off-tumor toxicity." (PMID 41348261, 2025). "In fact, MUC1 expression in normal pancreas cells begins to change concurrently with early genetic and molecular events, which lead to precursor lesions and tumor progression afterwards." (PMID 40001578, 2025). "In HNSCC, MUC1 expression is higher in tumor tissues compared to adjacent normal tissues, and it is associated with poor prognosis, advanced tumor stages, and resistance to radiation therapy." (PMID 40312353, 2025). "According to the expression of MUC1 in different subtypes of SCLC and the negative correlation with patient prognosis, we inferred that MUC1 is a distinguished biomarker for tumor growth and treatment of SCLC." (PMID 40349179, 2025). "Mucin 1 (MUC1) staining was used to identify tumour cells in liver tissues, confirming a reduction of the liver metastatic foci area in BBIT20-treated mice compared to the vehicle group." (PMID 40275348, 2025). "Bind to specific tumor-associated antigens (e.g., EGFR, MUC-1) to inhibit tumor growth or enhance immune response." (PMID 40881676, 2025). "We observed significant sex differences in tumor growth in the group that received the combined vaccine of MUC1 and TLR agonists in C3-liposomes." (PMID 40284463, 2025). "An early study of prophylactic MUC1 plasmid DNA (pMUC1) displayed limited efficacy in inducing tumor protection in a murine colorectal cancer model." (PMID 41012179, 2025). "MUC1 was predominantly expressed in neoplastic and malignant conditions, highlighting its potential as a marker of malignancy and tumor aggressiveness." (PMID 40821195, 2025). "Specifically, MUC1 regulates the TGF-β1 function switching from a tumor-suppressor to a tumor-promoter through phosphorylation of its C-terminal tyrosines independently by SMAD4 signaling." (PMID 40001578, 2025). "In T_EP, there was significant upregulation of genes associated with malignancy, such as EPCAM, HSPB1, CEACAM6, MUC1, and LY6E, implicating their roles in tumor initiation." (PMID 40786043, 2025). "The previous meta-analysis included studies detecting MUC1 in tumor tissue, mRNA concentrations of MUC1 in blood, and serum KL-6." (PMID 41041313, 2025). "WFDC2, along with NAPSA and MUC1, was upregulated in PD-L1–positive tumor cells, suggesting its potential role in immune evasion." (PMID 40723266, 2025). "A type I transmembrane glycoprotein, mucin 1 (MUC1) is overexpressed in hypoglycosylated form in over 80% of human cancers and is involved in the tumor immune evasion mechanism." (PMID 40437549, 2025). "One prominent example of a viral vector-based vaccine is PANVAC, a recombinant poxvirus vaccine designed to express two tumor-associated antigens: carcinoembryonic antigen (CEA) and mucin 1 (MUC1)." (PMID 40333213, 2025). "Mucin 1 (MUC1) is highly expressed in TC and correlates with tumor aggressiveness and poor prognosis." (PMID 41154432, 2025). "In cancer, MUC1 often exhibits aberrant glycosylation patterns, leading to altered interactions and roles in tumor invasion and metastasis." (PMID 40868286, 2025). "MUC1-mediated nuclear translocation of β-catenin and NF-kB complex modulates tumor cell survival, anchorage-independent growth, and drug resistance in MM cells in vitro." (PMID 40179083, 2025). "Three human ACC cell lines, either originating from a primary tumour (NCI‐H295R) or an ACC metastasis (MUC‐1 and TVBF‐7) were used." (PMID 39528354, 2025). "This therapy, incorporating a CD3-ζ signaling domain mutation (1XX mutation), significantly extends T cell survival and enhances the killing capacity against low MUC1-expressing tumor cells." (PMID 40655139, 2025).
tumor (continued). "This robust T-cell response in females vaccinated with MUC1 3Adj C3-liposome was notable, as these mice developed significantly larger tumors, suggesting the presence of systemic or localized tumor-induced immune suppression." (PMID 40284463, 2025). "In pathological conditions, MUC1 covers the surface of tumor cells and protects them from the cytotoxic components of cell-mediated immunity, masking tumor-associated antigens TAAs." (PMID 40001578, 2025). "Beyond its widely studied role in tumor biology due to its aberrant glycosylation and overexpression in cancer, MUC1 has recently emerged as a critical endogenous regulator of inflammation." (PMID 41181093, 2025). "MUC1 and mesothelin are tumor markers with potential targeting for ADCs, which have shown good results in clinical studies." (PMID 40507272, 2025). "This confirmed that stromal transcripts (Fap and Acta2) were mapped to the mouse genome, while tumor cell-intrinsic transcripts (MUC1 and KRT19) were human reads." (PMID 40508010, 2025). "Next, we performed comparative β-catenin immunofluorescence stainings in NCI-H295R, TVBF-7 and MUC-1 tumor spheroids." (PMID 41310103, 2025). "In a glioma mouse model, this self-adjuvant trivalent MUC1 vaccine, especially the trivalent vaccine, triggered a strong anti-tumor effect." (PMID 39861694, 2025). "MUC1, a glycoprotein with altered glycosylation, is a marker of tumor progression, immune escape, and resistance to chemotherapy." (PMID 40699746, 2025). "For instance, chemical exchange saturation transfer (CEST) MRI detects under-glycosylated MUC1 (uMUC1) in malignant tissues, providing a non-invasive method to assess tumor malignancy." (PMID 40655139, 2025). "By inducing DNA methyltransferase (DNMT) 1 and 3b, MUC1 also contributes to the suppression of tumor-suppressor genes via promoter-specific DNA methylation." (PMID 40699805, 2025). "The JAK/STAT signaling cascade and MUC-1 are pivotal drivers of immune evasion and tumor progression in TNBC." (PMID 40650040, 2025). "Further correlation analysis of the genes from cell cycle and cell adhesion modules revealed that MUC1 was not only highly correlated with the gene expression levels but also with the tumor status." (PMID 40349179, 2025). "Azurin secretion was shown to be associated with the exposure of bacteria to aldolase A secreted by tumor cells in the presence of P. aeruginosa, which, together with MUC-1 mucin, determines the adherence of P. aeruginosa to tumor cells." (PMID 39906620, 2025). "MUC1 interacts with various cells in the TME, including tumor-associated macrophages (TAMs), which are known to promote cancer growth and metastasis through the secretion of growth factors and cytokines." (PMID 40655139, 2025). "In specific, study reported that tumor cells showed expression levels of MUC1 (77%), MUC2 (2%), MUC5B (63%), MUC5AC (36%) and MUC6 (21%)." (PMID 40655139, 2025). "MUC1 promotes the separation of tumor cells from the extracellular matrix, thereby enhancing cellular dispersion and facilitating early LNM." (PMID 41583217, 2025). "Given its role in tumor progression and extracellular location, MUC1 represents a strong candidate TAA for therapeutic vaccination." (PMID 41542091, 2025). "Tumor inhibition was significantly more effective when vaccination with MUC1 mRNA-loaded NLE was combined with silencer blockade of CTLA-4." (PMID 40943370, 2025). "Several studies have shown that siRNA-mediated knockdown of tumor-associated genes such as TGM2, EGFR, and MUC1 in solid tumors can effectively reduce tumor proliferation and enhance apoptotic pathways." (PMID 41425727, 2025). "Studies have shown that dual-targeted CAR-T cells, such as those designed to target both MUC1 and ErbB2, can efficiently eliminate tumor cells expressing either MUC1 or ErbB2." (PMID 40312353, 2025).